POLR2E (RNA polymerase II, I and III subunit E)
Description:
DNA-dependent RNA polymerase catalyzes the transcription of DNA into RNA using the four ribonucleoside triphosphates as substrates. Common component of RNA polymerases I, II and III which synthesize ribosomal RNA precursors, mRNA precursors and many functional non-coding RNAs, and small RNAs, such as 5S rRNA and tRNAs, respectively. Pol II is the central component of the basal RNA polymerase II transcription machinery. Pols are composed of mobile elements that move relative to each other. In Pol II, POLR2E/RPABC1 is part of the lower jaw surrounding the central large cleft and thought to grab the incoming DNA template.
Synonyms: RPB5; RPABC1; XAP4; hRPB25; hsRPB5
Tractability: Small molecule: a structure with a bound ligand is known. PROTAC: UniProt records ubiquitination sites on it; ubiquitination databases record sites on it; its protein half-life has been measured.
Gene: Protein-coding gene on chromosome 19 (1,085,104 to 1,095,389, reverse strand). Ensembl gene ENSG00000099817.
Subcellular location: Nucleus; Nucleus, nucleolus
Subcellular location (Human Protein Atlas): Nucleoplasm
Pathways (Reactome):
Gene expression (Transcription): B-WICH complex positively regulates rRNA expression; Formation of RNA Pol II elongation complex; Formation of the Early Elongation Complex; MicroRNA (miRNA) biogenesis; NoRC negatively regulates rRNA expression; PIWI-interacting RNA (piRNA) biogenesis; RNA Pol II CTD phosphorylation and interaction with CE; RNA Polymerase I Promoter Escape; RNA Polymerase I Transcription Initiation; RNA Polymerase I Transcription Termination; RNA Polymerase II Pre-transcription Events; RNA Polymerase II Promoter Escape; RNA Polymerase II Transcription Elongation; RNA Polymerase II Transcription Initiation; RNA Polymerase II Transcription Initiation And Promoter Clearance; RNA Polymerase II Transcription Pre-Initiation And Promoter Opening; RNA Polymerase III Abortive And Retractive Initiation; RNA Polymerase III Chain Elongation; RNA Polymerase III Transcription Initiation From Type 1 Promoter; RNA Polymerase III Transcription Initiation From Type 2 Promoter; RNA Polymerase III Transcription Initiation From Type 3 Promoter; RNA Polymerase III Transcription Termination; RNA polymerase II transcribes snRNA genes; Transcriptional regulation by small RNAs
Disease: Abortive elongation of HIV-1 transcript in the absence of Tat; Dengue Virus-Host Interactions; Formation of HIV elongation complex in the absence of HIV Tat; Formation of HIV-1 elongation complex containing HIV-1 Tat; Formation of the HIV-1 Early Elongation Complex; HIV Transcription Initiation; HIV elongation arrest and recovery; Pausing and recovery of HIV elongation; Pausing and recovery of Tat-mediated HIV elongation; RNA Pol II CTD phosphorylation and interaction with CE during HIV infection; RNA Polymerase II HIV Promoter Escape; Signaling by FGFR2 IIIa TM; Tat-mediated HIV elongation arrest and recovery; Tat-mediated elongation of the HIV-1 transcript; Transcription of the HIV genome
and 15 more pathways
Gene Ontology:
Molecular function: protein binding; DNA-directed RNA polymerase activity; DNA binding
Biological process: termination of RNA polymerase III transcription; transcription by RNA polymerase II; transcription by RNA polymerase III; transcription elongation by RNA polymerase I; transcription elongation by RNA polymerase II; transcription initiation at RNA polymerase II promoter; transcription initiation at RNA polymerase III promoter; nucleolar large rRNA transcription by RNA polymerase I; protein stabilization; termination of RNA polymerase I transcription; transcription initiation at RNA polymerase I promoter; tRNA transcription by RNA polymerase III; DNA-templated transcription
Cellular component: nucleoplasm; nucleus; RNA polymerase I complex; RNA polymerase II, core complex; RNA polymerase III complex; RPAP3/R2TP/prefoldin-like complex; cytosol; nucleolus
Genetic constraint (gnomAD): Loss-of-function variants: 31 observed, 27.47 expected, observed/expected ratio (o/e) 1.13, 90% interval 0.85 to 1.52. The synonymous counts are far from expectation, so gnomAD's model fits this gene poorly and the ratio says little. Missense variants: 284 observed, 296.16 expected, observed/expected ratio (o/e) 0.96, 90% interval 0.87 to 1.06. Synonymous variants: 173 observed, 117.2 expected, observed/expected ratio (o/e) 1.48, 90% interval 1.3 to 1.67.
Homologues: Orthologues: chimpanzee POLR2E (99% identical), dog POLR2E (99% identical), guinea pig POLR2E (99% identical), mouse Polr2e (99% identical), rat Polr2e (99% identical), tropical clawed frog polr2e (97% identical), pig POLR2E (97% identical), zebrafish polr2eb (94% identical), zebrafish POLR2E (93% identical), Drosophila melanogaster Polr2E (85% identical), Caenorhabditis elegans rpb-5 (77% identical), macaque POLR2E (57% identical).
Diseases named in the same sentence as POLR2E in open-access papers:
POLR2E is named in the same sentence as 19 diseases in open-access papers, as found by Europe PMC text mining. Sharing a sentence is not in itself a finding about the gene and the disease. The quoted sentences say what the papers report.
prostate carcinoma (4 papers, 2017 to 2024). A carcinoma that arises from epithelial cells of the prostate gland. "A systematic review and meta-analysis of 5 studies on the role of rs3787016 within POLR2E has revealed increased susceptibility to prostate cancer for carriers of T allele in all genotype models." (PMID 37025585, 2023). "The rs3787016 polymorphism, locates in an intron of POLR2E gene, was first reported in a genome-wide association study of prostate cancer." (PMID 30291213, 2018). "We hypothesized that polymerase II polypeptide E (POLR2E) rs3787016 polymorphism, identified in a genome-wide association study of prostate cancer, might be a common genetic risk factor for cancer risk." (PMID 30291213, 2018). "Contribution of single nucleotide polymorphisms (SNPs) within GAS5, POLR2E, MEG3, MALAT1 and HOTAIR in the risk of prostate cancer has been assessed in different ethnic groups." (PMID 37025585, 2023). "With the development of high throughput chip and sequencing technology, a variety of lncRNAs have been investigated, e.g. HOX transcript antisense RNA (HOTAIR), prostate cancer non-coding RNA1 (PRNCR1), RNA polymerase II polypeptise E gene (POLR2E)." (PMID 28159929, 2017).
esophageal cancer (3 papers, 2017 to 2024). A primary or metastatic malignant neoplasm involving the esophagus. "For POLR2E, we found that rs3787016 increased the risk of esophageal cancer (recessive model: 1.76, 1.25-2.49)." (PMID 28159929, 2017). "HOTAIR rs920778 may serve as a potential therapeutic suppression target, while POLR2E rs3787016 may represent a valuable biomarker to evaluate esophageal cancer predisposition and predict treatment response and prognosis." (PMID 38300349, 2024). "Hence, we explored the contribution of four long non-coding RNAs’ polymorphisms HOTAIR rs920778, LINC00951 rs11752942, POLR2E rs3787016 and HULC rs7763881 in esophageal cancer susceptibility." (PMID 38300349, 2024).
cervical cancer (2 papers, 2024). A primary or metastatic malignant neoplasm involving the cervix. "SNP rs3787016 (A>G or its complementary T>C, C/T), localized in the fourth intron of the RNA polymerase II subunit E (POLR2E) lncRNA gene, has been implicated with cancer susceptibility either by predisposing for GC, breast and cervical cancer, or by protecting against ESCC in Chinese populations." (PMID 38339289, 2024).
lung carcinoma (2 papers, 2018 to 2023). "To date, no study has been conducted to investigate the association between the risk of liver or lung cancer and POLR2E rs3787016 polymorphism." (PMID 30291213, 2018). "In view of this, a case–control study, based on 480 liver cancer patients, 550 lung cancer patients, and 800 normal controls, was conducted to evaluate the association between POLR2E rs3787016 and risk of lung and liver cancer in a Chinese population of Hubei province." (PMID 30291213, 2018).
alcohol (1 paper, 2025). "In summary, we delineate a novel pathway in which dietary glutamine stabilizes GLS1, enabling its nuclear interaction with POLR2H/POLR2E to suppress RNA pol II activity and attenuate alcohol‐induced hepatic steatosis." (PMID 40936098, 2025). "Moreover, the overexpression of POLR2E or POLR2H, but not the truncated variants, abolishes the protective effects of GLS1 against alcohol‐induced fatty liver." (PMID 40936098, 2025).
Hepatic steatosis (1 paper, 2025). Steatosis is a term used to denote lipid accumulation within hepatocytes. "Mechanistically, glutamine was found to stabilize GLS1, thereby promoting its interaction with RNA polymerase subunit H (POLR2H) and RNA polymerase subunit E (POLR2E), which reduced the activity of RNA pol II, affecting hepatic steatosis in AFLD." (PMID 40936098, 2025). "Our findings demonstrate that GLS1 interacts with the RNA pol II subunits POLR2H and POLR2E to modulate RNA pol II transcriptional activity, thereby promoting hepatic steatosis in AFLD." (PMID 40936098, 2025). "Collectively, these findings demonstrate that in the liver, GLS1 ameliorates alcohol‐induced fatty liver through its interaction with POLR2H or POLR2E." (PMID 40936098, 2025).
melanoma (1 paper, 2020). A malignant, usually aggressive tumor composed of atypical, neoplastic melanocytes. "Among these kinases, 6 (RPS6KB2, DSTYK, TBRG4, CDK4, POLR2E, FASTKD5) and 4 (STK26, PAK1, EPHB2 and JAK3) were consistently up- or down-regulated, respectively, in the metastatic lines of at least two pairs of melanoma cells." (PMID 32051510, 2020).
cancer (8 papers, 2017 to 2024). A tumor composed of atypical neoplastic, often pleomorphic cells that invade other tissues. "For example, the CpG site cg18608055 (proximal to SBNO2) was associated with POLR2E, an RNA polymerase associated with cancer which also contributed to the significant KEGG cytosolic DNA-sensing pathway." (PMID 38571307, 2024). "Rs3787016, which localizes to the fourth intron of RNA polymerase II polypeptide E (POLR2E) gene, has been studied by several researchers on its association with cancer risk." (PMID 30291213, 2018). "In recent studies, most of meta-analyses were conducted to focus on the association between lncRNA HOTAIR or lncRNA ZNRD1-AS1 or lncRNA POLR2E or lncRNA H19 polymorphisms and cancer risk." (PMID 29802154, 2018). "In conclusion, our meta-analysis showed that lncRNA HOTAIR rs920778, PRNCR1 rs1016343 and rs16901946, POLR2E rs3787016 were associated with cancer susceptibility." (PMID 28159929, 2017). "The results indicate that these four lncRNAs polymorphisms (HOTAIR rs920778, PRNCR1 rs1016343 and rs16901946, POLR2E rs3787016) can contribute to the increased risk of cancer." (PMID 28159929, 2017). "For PRNCR1 (rs1016343, rs16901946) and POLR2E (rs3787016), we also found the significant association with incresed risk of cancer (all P<0.05)." (PMID 28159929, 2017). "Our meta-analysis results revealed that these four lncRNAs polymorphisms (HOTAIR rs920778, PRNCR1 rs1016343 and rs16901946, POLR2E rs3787016) can contribute to cancer risk." (PMID 28159929, 2017). "In these 38 included articles, we observed that a variety of lncRNA genes had been investigated the association with cancer risk, among which lncRNA HOTAIR, PRNCR1, H19, and POLR2E had been widely studied." (PMID 28159929, 2017). "Herein, we conducted a meta-analysis to summarize all eligible case-control studies to evaluate the overall cancer risk and common lncRNAs (HOTAIR, PRNCR1, H19, and POLR2E) polymorphisms." (PMID 28159929, 2017). "By contrast, some other genes encoding the polymerase II subunits were characterized by higher methylation in carcinomas than in BOTS (e.g., promoters and/or first exons of POLR2G and POLR2L, as well as the distal promoter of POLR2C, and the cds of POLR2E, GR file)." (PMID 39456618, 2024).
tumor (3 papers, 2020 to 2022). "Genes associated with the SEs in tumor cells were mostly related to transcription (e.g., POLR2E, PARK7, MYC)." (PMID 33168807, 2020). "RAD21, BOP1, POLR2E, and PRKDC were mainly expressed in tumor cells, RIPK2 was mainly expressed in monocytes, MAP2K2 was mainly expressed in tumor cells and macrophages, NBN was mainly expressed in macrophages and monocytes, and GPX4 was mainly expressed in tumor cells and T cells." (PMID 36212155, 2022).
POLR2E also shares sentences with these, for which no sentence is quoted: acute myeloid leukemia (1 paper); Alzheimer disease (1); cataract (1); gastric cancer (1); gastrointestinal disease (1); hepatitis B virus infection (1); liver cancer (1); metabolic disorders (1); neurodevelopmental disorder (1); overnutrition (1).